SIRT6 (sirtuin 6)
Diseases named in the same sentence as SIRT6 in open-access papers (continued):
Sharing a sentence is not in itself a finding about the gene and the disease.
cancer (continued). "SIRT6 suppress cell proliferation via Twist1, which is also a key factor in the promotion of metastasis of cancer cells." (PMID 29515203, 2018). "SIRT6 activity promotes apoptosis in numerous cell types, thus its activation is suggested to be beneficial for certain cancers." (PMID 30409187, 2018). "Taken together, these results clearly demonstrate that pharmacological activation of SIRT6 triggers an increase of autophagy that results in apoptosis in different human cancer cells." (PMID 30250025, 2018). "Several studies propose that SIRT6 is an attractive target for activation, as it is shown to suppress survival of cancer cells and extend longevity in whole body overexpressing mice." (PMID 30409187, 2018). "Sirtuin-6 (SIRT6) is an NAD+-dependent histone deacetylase that plays an important role in various biological events such as cancer, longevity, DNA-repair, and inflammation." (PMID 30104534, 2018). "SIRT6 was recently shown to regulate metabolic reprogramming in cancer cells via metabolic signaling pathways decreasing the expression of glycolytic genes, including GLUT1 and HIF1-alpha and decreasing glucose uptake and lactate formation by cells." (PMID 29515203, 2018). "To this aim, we analyzed the proliferation rate of cancer cells exposed to different doses of the SIRT6 activator UBCS039 or the chemical inactive analog UBCS060." (PMID 30250025, 2018). "When mice are deprived of SIRT6, they exhibit phenotypes along the lines of shortened life expectancy, cancer, and metabolic disorders." (PMID 29966233, 2018). "SIRT6 knockout induced a shift towards a ‘glycolytic phenotype’ and promoted cancer formation and aggressiveness." (PMID 28092669, 2017). "SIRT6 plays a role in genomic instability and DNA repair and inflammation explains SIRT6 participation in cancer." (PMID 28197299, 2017). "Alteration in glucose metabolism is now considered as a common feature of cancer and SIRT6 can repress a number of enzymes involved in the homeostatic control of glucose metabolism in cancer cells." (PMID 27659520, 2017). "SIRT6 acts as an eraser, removing the fatty acyl group, and therefore slows down the growth of cancer cells." (PMID 28406396, 2017). "Based on limited available information to date, the role of SIRT6 in cancer is somewhat controversial." (PMID 29234488, 2017). "In contrast with our observations, SIRT6 expression was reported to be lower in HCC tissue than in normal liver tissue based on an analysis of the publically available Oncomine Cancer Microarray database." (PMID 27824900, 2016). "Crucial roles of SIRT6 in DNA repair, metabolism, and inflammation which are associated with cancer have prompted much investigation into the role of SIRT6 in cancer progression." (PMID 27824900, 2016). "In conclusion, these findings provide a valuable insight toward the development of pharmacological SIRT6 activators for ageing-related diseases including neurodegenerative diseases, metabolic diseases and cancer." (PMID 27156849, 2016). "SIRT6 is overexpressed in several cancers, including prostate and endometrioid carcinomas, and keratinocyte-derived skin squamous cell carcinomas." (PMID 27777384, 2016). "In human HCC, SIRT6 inhibits survivin to control cancer initiation via an AP-1-dependent regulatory network." (PMID 27777384, 2016). "Subsequent studies link SIRT6 with genomic stability, DNA repair, glucose metabolism, cancer, lipid metabolism, inflammation and heart disease." (PMID 27794562, 2016).
cancer (continued). "This study also identified downregulation of SIRT6 in several forms of human cancer, such as pancreatic and colorectal cancer." (PMID 25907989, 2015). "Clearly, further studies are needed to clarify the opposing roles of SIRT6 in cancer, and to investigate the therapeutic potential of SIRT6 in established tumors." (PMID 25085992, 2014). "Elevated SIRT6 levels have been reported in pancreatic, breast and prostate carcinomas where SIRT6 contributes to cell migration, enhanced cell viability and chemotherapeutic resistance." (PMID 25085992, 2014). "Sirt6 is known to regulates aerobic glycolysis in cancer cells and the down-regulation of Sirt6 is observed in several human cancers." (PMID 23593434, 2013). "SIRT6 regulates multiple chromatin-based processes relevant to cancer." (PMID 41463311, 2025). "Furthermore, according to the Cancer Cell Line Encyclopedia report, more than one-third of cancer cell lines included in their database contain a deletion of the SIRT6 gene." (PMID 40149343, 2025). "Sirtuin 6 (SIRT6), a member of the class III histone deacetylase (HDAC) family, is crucial for the maintenance of general health and is associated with increased life expectancy and resistance to age-related diseases such as cancer and metabolic disorders." (PMID 40416060, 2025). "Specifically, SIRT6 frequently restrains oncogenic glycolysis in cancer cells." (PMID 41463311, 2025). "In muscle tissues, SIRT6 expression also plays a protective role against inflammation and cancer." (PMID 40806744, 2025). "As such, SIRT6 activation or inhibition may be beneficial depending on other specific type of cancer." (PMID 39845013, 2025). "Meanwhile, related studies have shown that SIRT3, SIRT4 and SIRT6 also inhibit the Warburg effect and exert anticancer effects by regulating components of the phosphatidylinositol-3 kinase pathway, which is central to cancer metabolism." (PMID 40292294, 2025). "Similar to other SIRTs, SIRT6 has a double‐faced role in cancer, depending on the specific context." (PMID 39215785, 2025). "Developing subtype-specific SIRT6 modulators, combined with advanced biomarker-driven patient stratification, may unlock novel combinatorial regimens for precision oncology aimed at cancer prevention, treatment optimization, and metastasis suppression." (PMID 41463311, 2025). "Furthermore, fluvastatin treatment has been shown to increase SIRT6 expression, and the resulting elevation in SIRT6 levels is thought to contribute to its anti-cancer effects." (PMID 41471349, 2025). "Therefore, enhanced expression or activation of SIRT6 offers potential for mitigating cancer cachexia and enhancing patient survival." (PMID 39971710, 2025). "Given its pleiotropic activity at different levels of cellular homeostasis, it is not surprising that dysregulation of SIRT6 is also associated with cancer." (PMID 39215785, 2025). "Several Sirt6−/− mice developed fibrosis and cancer in the liver." (PMID 38332150, 2024). "By leveraging a reversed allosteric strategy to uncover the cryptic site Pocket Z, JYQ-42 not only achieves the selective inhibition of SIRT6 but also significantly curtails cancer cell migration and pro-inflammatory cytokine production, both of which are pivotal in the metastatic cascade." (PMID 39682281, 2024). "Interestingly, the anti-cancer effect of Sirt6 seems more apparent in interaction with Sirt1, inducing MDM2-dependent Sirt1 degradation or potentiating the DNA damage response." (PMID 38254877, 2024). "Sirt6 exhibits anti-cancer effects in many malignancies; however, whether Sirt1 acts as a pro-tumorigenic or anti-tumorigenic factor remains unclear." (PMID 38254877, 2024). "Specifically, the potential involvement of SIRT6 in cancer cell anoikis remains unexplored." (PMID 38891773, 2024). "Further exploration is needed to figure out whether the accelerated cell proliferation of SIRT6 KD granulosa cells shares the same mechanism as in cancer cells." (PMID 37936548, 2024).
cancer (continued). "Moreover, SIRT6’s ability to modulate inflammatory responses adds another layer of complexity to its role in cancer." (PMID 39682281, 2024). "UBCS039 binds to the SIRT6-specific acyl channel pocket and can induce autophagy in cancer cells." (PMID 39479446, 2024). "Sirt6 has been shown to act as a cancer suppressor in many studies." (PMID 38332150, 2024). "This strategic modulation of SIRT6 activity may pave the way for innovative cancer therapies, enabling personalized treatment regimens that exploit the unique regulatory mechanisms SIRT6 offers in combating this formidable malignancy." (PMID 39682281, 2024). "Considering the central role of SIRT6 in cellular homeostasis, it has emerged as a target for the development of numerous small-molecule activators and inhibitors possessing therapeutic potential in cancer." (PMID 37958565, 2023). "Our result also suggests that SIRT6 inhibitor might be helpful for improving sensitivity of DNA-target chemotherapeutic agents in cancer and we might conduct more in-depth research on this aspect in the future." (PMID 37542062, 2023). "SIRT6-mediated regulation of eNAMPT release occurs by modulating the iNAMPT acetylation status in cancer cells, contrasting with the SIRT1-mediated secretion of eNAMPT from the adipose tissues, although the precise mechanisms for these different regulation patterns are currently being investigated." (PMID 36986224, 2023). "SIRT6 plays an important role in the cytoprotective effect of multiple diseases, including cancer." (PMID 38235110, 2023). "Furthermore, the acetylation status of iNAMPT is regulated by another nuclear SIRT, SIRT6, in cancer cells." (PMID 36986224, 2023). "Consequently, based on our current study, we believe that Ethyl 2-[5-(4-chlorophenyl)-2-methyl-1-H-Imidazole-4-yl] acetate potentially inhibits nuclear sirtuins, especially the expression of Sirt6 and regulates cancer progression." (PMID 38020163, 2023). "SIRT6 has been shown to have multiple effects on cell survival and cancer progression." (PMID 37175631, 2023). "Based on these studies, we hypothesized that SIRT6 inhibitor can lead to cancer cells sensitivity to DNA damaging agents in cancer chemotherapy by blocking DNA repair." (PMID 37542062, 2023). "In addition, activators of H3K18 deacetylase SIRT6, which are a class of anti-cancer agents, can be used in the same way to inhibit the overexpression of satellite DNA." (PMID 37958565, 2023). "Finally, SIRT6 regulates the transmission of Wnt/β-catenin signals, which contribute to the progression of cancer." (PMID 37175631, 2023). "A better understanding of factors influencing SIRT6 expression and its biological role in carcinogenesis may help to develop novel anti-cancer therapeutic strategies." (PMID 38203666, 2023). "Moreover, we discuss the anti-cancer effects and mechanism of action of small molecule SIRT6 modulators (both activators and inhibitors) in different types of cancer." (PMID 38203666, 2023). "Therefore, we propose a new mechanism of ADORA2A-mediated metabolic-epigenetic cascade via the ERK/MYC/PYCR/SIRT6/7 axis in promoting lineage plasticity and resistance to targeted therapy in cancer cells." (PMID 38099497, 2023). "A better understanding of the factors influencing SIRT6 expression and its biological role in carcinogenesis may help to develop novel anti-cancer therapeutic strategies." (PMID 38203666, 2023). "The goal of this study is to further elucidate the role of SIRT6 in mammalian solid tumours by meta-analysis and the TCGA dataset, which may aid in the detection and treatment of certain cancers." (PMID 35172823, 2022). "In addition to its role in cellular progression and cancer, SIRT6, a member of nicotinamide adenine dinucleotide (NAD+)-dependent class III deacylase sirtuin family, serves a variety of roles in the body's immune system." (PMID 35172823, 2022).
cancer (continued). "For instance, one reason to consider SIRT-6 as an oncosuppressor is represented by the shift from aerobic respiration to glycolysis observed in SIRT6-deficient cells resembling the Warburg effect, typical of cancer cells." (PMID 36080416, 2022). "If SIRT6 is to be used to regulate the development of cancer via effects on the metabolism, proliferation, and apoptosis of cancer cells, it will be necessary to conduct a very comprehensive study of its role in the occurrence and development of various cancers." (PMID 35463332, 2022). "SIRT6 also regulates the development process of cancer, an aging-related disease." (PMID 35463332, 2022). "Cancer-related studies suggest that SIRT6 is a double-edged sword." (PMID 36117172, 2022). "However, studies have shown that patients with low nuclear expression of SIRT6 have cancer that is more aggressive and shorter survival." (PMID 35463332, 2022). "Given the involvement of SIRT6 in BC progression, inhibition of SIRT6 may represent a successful strategy for cancer management." (PMID 35927590, 2022). "This set of data suggests that SIRT6 regulates the metabolic flux in the cancer cells by increasing metabolic rate which might facilitate cell invasion." (PMID 35686673, 2022). "Among them, Sirtuin‐6 (SIRT6) has emerged as a crucial member with regulatory roles in aging, metabolism, DNA damage repair, lifespan determination, fat mobilization, stress response, apoptosis, autophagy, and cancer." (PMID 35686673, 2022). "Our findings indicate that the cancer metabolic pathway regulated by SIRT6 may be a new target for attenuating NSCLC erlotinib resistance and has potential as a biomarker or therapeutic target to improve outcomes in NSCLC patients." (PMID 35915188, 2022). "Sirt6 has emerged as a promising target for the development of small-molecule activators and inhibitors possessing therapeutic potential in diseases ranging from cancer to age-related disorders." (PMID 36490326, 2022). "Overall, our findings suggest that RV directly modulates PPARα-mediated L1-RTP in somatic cells and that MAPK signaling interacts with SIRT6 closely and may play a role in preventing human diseases such as cancer." (PMID 35546166, 2022). "Therefore, this representation shows the coordination of cancer‐pathway‐related genes with the players of mitochondrial function and metabolic regulation, predicting their importance in SIRT6‐induced cancer cell modulation." (PMID 35686673, 2022). "Among the phosphoproteins, we validated four enzymes associated with cancer and present only in sEVs isolated from MCF7 and MDA-MB-231 cell lines: ATP citrate lyase (ACLY), phosphofructokinase-M (PFKM), sirtuin-1 (SIRT1), and sirtuin-6 (SIRT6)." (PMID 35203617, 2022). "Substrates and enzymatic activity of SIRT6 during aging, immunity, and cancer regulation." (PMID 35463332, 2022). "In this study, we noted that SIRT6 may play important roles in the inflammation-carcinoma sequence, particularly in IM." (PMID 36324577, 2022). "Furthermore, the role of SIRT6 on the induction of the DNA damage repair pathway strongly supports its role in the prevention of cancer development." (PMID 34359939, 2021). "Thus, it is possible that cancer cells with low SIRT6 will show increased uptake of other mitochondrial fuels, such as glutamine and fatty acids." (PMID 33482921, 2021). "In this review, we scrutinize the functions of SIRT6 in the regulation of cell death and cancer." (PMID 33800266, 2021). "Upregulation of SIRT6 arrests cancer development through survivin’s anti-apoptotic activity." (PMID 33920726, 2021). "Therefore, SIRT6 is involved in many kinds of aging related disease such as neurodegenerative disease, cancer, CVDs." (PMID 33855020, 2021). "In this review, we aim to summarize the current knowledge on the role of SIRT6 in cancer." (PMID 33800266, 2021).
cancer (continued). "In order to see the big picture, it would be important to screen changes in SIRT6 levels in many kinds of cancer cell lines which may help to discover safe individual-specific treatments for cancer." (PMID 33684691, 2021). "SIRT6 inhibitors are found to inhibit cancer cell growth and promote apoptosis." (PMID 33920726, 2021). "The effects of Sirt6 and Sirt1 combine to regulate ROS-induced cancer cell death." (PMID 33727672, 2021). "SIRT6 isa nuclear protein, which can regulate various cellular pathways, including transcriptional control, metabolism, DNA repair and genomic stability, proliferation and differentiation, cancer and more." (PMID 34927546, 2021). "Furthermore, SIRT6 expression in cancer tissues of patients with metastatic CRC was also lower than that in cancer tissues of patients with primary CRC." (PMID 33510943, 2021). "SIRT6 can act as both a cancer promoter and a cancer suppressor." (PMID 33920726, 2021). "Given the double-faced involvement of SIRT6 in cancer and inflammation, the inhibition of SIRT6 in specific contexts may also represent a successful strategy for cancer treatment." (PMID 33800266, 2021). "While SIRT6 over‐expression is reported to cause apoptosis in many cancer cell lines that was not the case with normal untransformed cells." (PMID 34212132, 2021). "Given its central role in cellular homeostasis, SIRT6 hasemerged as a promising target for the development of small-moleculeactivators and inhibitors possessing a therapeutic potential in diseasesranging from cancer to age-related disorders." (PMID 34213345, 2021). "The unique expression profiles of SIRT6 and other sirtuins may be a characteristic feature in different types of cancers, and different stages of tumorigenesis." (PMID 33684691, 2021). "Therefore, in conjunction with previous reports and this study, it is suggested that the CSNK2A1-mediated phosphorylation of SIRT6 on Ser338 is important in rescuing injured cancer cells by repairing DNA damage induced by anti-cancer therapeutics." (PMID 34359939, 2021). "The controversial role of SIRT6 in the pathogenesis of cancers may be tissue- and context-dependent." (PMID 34702956, 2021). "Previous studies have shown that nicotinamide is an inhibitor of SIRT6; therefore, suppressing nicotinamide can lead to SIRT6 protective effect against premature aging, hindering cancer growth, reducing the expression of IL8 and TNF as well as the reduction of serum glucose level." (PMID 33920726, 2021). "In addition, controversially, there were opposing reports on the role of SIRT6 in the same cancer type." (PMID 34359939, 2021). "Many SIRT6 activators have been recently developed and tested in cancer studies." (PMID 34650436, 2021). "Therefore, therapies targeting SIRT6 or the downstream DNA damage repair pathway have been suggested for cancers highly expressing SIRT6." (PMID 34359939, 2021). "Furthermore, SIRT6 promoted autophagy through the ROS-mediated activation of the AMPK pathway in cancer cell lines." (PMID 32983963, 2020). "However, the impact of SIRT6 on the proliferation of cancer cells has been reported controversially." (PMID 33198792, 2020). "Considering the role of SIRT6 as an inducer of DNA damage repair, it might be involved in resistance to anti-cancer therapy." (PMID 33198792, 2020). "Therefore, SIRT6 as a new epigenetic target is currently attracting increasing interest to solve the current dilemma in cancer treatment." (PMID 32483423, 2020). "Therefore, further study focusing on the role of SIRT6 according to the specific type of cancer is needed." (PMID 33198792, 2020). "Recent studies showed that Sirt6 promoted the Warburg effect of cancer cells via upregulation of reactive oxygen species (ROS), inhibition of ROS in Sirt6-upregulated cells could rescue activation of the Warburg effect." (PMID 32711549, 2020).